LEP (leptin)
Diseases named in the same sentence as LEP in open-access papers (continued):
Sharing a sentence is not in itself a finding about the gene and the disease.
Obesity (continued). "Furthermore, excessive cytokines, such as interleukin (IL)-6, IL-8, monocyte chemoattractant protein-1 (MCP-1), and leptin produced by the dysfunctional adipocytes in obesity, leads to increased recruitment of macrophages." (PMID 33546633, 2021). "Leptin is more than a centrally-acting mediator of appetite; macrophages are more than just co-opted inflammatory bystanders; norepinephrine is a potent fat burner, constrained by SAMs that accumulate in obesity." (PMID 34613819, 2021). "In contrast, hyperinsulinemia may, in turn, exacerbate obesity and further increase leptin levels, resulting in a positive feedback loop that promotes the development of diabetes." (PMID 34368053, 2021). "Furthermore, many genetic models have proven that the leptin gene’s absence induces obesity in animals and in humans." (PMID 34684349, 2021). "Being a well-known biomarker for obesity, leptin correlated positively with MUO-related PP5." (PMID 34659828, 2021). "In conditions like metabolic syndrome, overweight/obesity and Type 2 diabetes, there is increased body weight, insulin resistance, hyperglycemia, hypertension, and metabolic dysfunction including elevated levels of leptin and resistin." (PMID 33679451, 2021). "This may also represent the need to store more energy to adapt to the obesity status of requiring more energy storage and, therefore, more insulin (and also more leptin, for which a resistance also develops during obesity)." (PMID 33450943, 2021). "Obesity is also accompanied by changes in the circulating abundances of key adipokines involved in appetite regulation, including suppressed adiponectin and increased leptin concentrations." (PMID 34149621, 2021). "Leptin is an adipocytokine primarily produced by adipocytes, which, through its pro-inflammatory properties, is implicated in promoting several pathological conditions, such as T2DM, obesity, and cancer." (PMID 34360753, 2021). "Leptin exerts beneficial effects on metabolism by suppressing appetite and increasing the metabolic rate, mitigating obesity." (PMID 34276408, 2021). "Diet-induced obesity leads to leptin resistance, exacerbating overeating." (PMID 34899599, 2021). "Additionally, other parameters related to obesity or metabolic syndrome, such as Leptin, IGF, Insulin, or Adiponectin were measured during postnatal ages." (PMID 34281107, 2021). "However, DDE postnatal exposure showed a significant relationship with other indicators related to obesity, such as leptin concentration in serum of adolescent boys." (PMID 34281107, 2021). "In general, obesity is characterized by chronic inflammation and increased expression and release of proinflammatory neurohumoral factors, including adipokines such as leptin and adiponectin, and proinflammatory cytokines such as tumor necrosis factor-α (TNF-α), interleukin (IL)-1 and IL-6." (PMID 34088886, 2021). "Therefore, it is feasible to assume that PTP1B is directly involved in the regulation of obesity through its action on both IR and leptin signaling, and indirectly through of the modulation of the inflammatory response and recruitment of immune cells." (PMID 34726241, 2021). "In summary, our study concluded that the increase of serum leptin level may be an initiating factor of obesity-related OA, which further elevated the level of leptin in SF and induce the JAK2-STAT3 signaling pathway to promote the development of OA." (PMID 34457118, 2021). "According to Hassanzadeh-Rostami and Faghih, soluble or insoluble dietary fibre intake seem to not produce changes in leptin values in the short term but may reduce leptin levels in the long term in people with obesity." (PMID 34828792, 2021). "Obesity was mainly measured by the body mass index, although other common types of evaluations were used (e.g., waist circumference, waist-to-hip ratio and plasma leptin levels)." (PMID 34439618, 2021).
Obesity (continued). "Therefore, we identified leptin, which was mainly produced by adipose tissue and recognized as a critical adipokine linking obesity to cancer, as a candidate molecule to analyze its role in breast cancer." (PMID 34970222, 2021). "For example, in humans, the response of obese subjects to weight loss is fundamentally intact, suggesting that the ‘extra’ leptin in the context of obesity is able to exert relevant biological effects on other mechanisms besides those involved in the control of feeding." (PMID 34208585, 2021). "The causes of the elevated sympathetic nerve activity observed in obesity are unknown but leptin contributes." (PMID 33679451, 2021). "In addition to obesity, lipid metabolism disorders, systemic inflammatory responses, and oxidative stress, leptin levels were also affected by sex differences, circadian rhythm of leptin secretion, metabolic disease, and lifestyle, among others." (PMID 34671315, 2021). "However, while obesity-related infertility is becoming increasingly common, it is nevertheless possible to exhibit resistance to leptin’s ‘anti-obesity’ effects while remaining fertile." (PMID 34502119, 2021). "In obesity, its hypertrophy is directly related to chronic low-grade inflammation and an increase in chemotactic molecules, in addition to a reduction in adiponectin levels and the onset of leptin resistance." (PMID 33807959, 2021). "The importance of leptin genes and modulation of leptin action and protein expression in Ossabaw pigs were indicated in previous studies, providing stimulus for future obesity and disease studies on these genes." (PMID 34585119, 2021). "Some studies have also shown that leptin, as a regulator of serum uric acid concentration, may be an intermediate factor between obesity and hyperuricemia." (PMID 33514431, 2021). "They examined whether high-fat diet-induced-obesity in fathers before conception would impact the metabolic status of offspring, as seen by the epigenetic status of the adiponectin and leptin gene promotors in a mouse model." (PMID 33445606, 2021). "Consequently, hypothalamic inflammation and injury result in leptin resistance and thus impaired control of food intake, thereby propelling obesity." (PMID 34201844, 2021). "It has also been stated that leptin induces an inflammatory phenotype in murine alveolar macrophages, hinting that a higher concentration of leptin in obesity might be potentiating the incidence of pulmonary inflammation in COVID-19 infection." (PMID 34220807, 2021). "IgG leptin-neutralizing autoantibodies were found in healthy subjects with a lower BMI; however, a decreased affinity of these antibodies was found in obese patients, which might be relevant to leptin resistance in obesity." (PMID 33953692, 2021). "Leptin, sOB‐R and PAI‐1 were also similarly unrelated to risk of obesity‐related cancers." (PMID 33038280, 2021). "In obesity, leptin levels can be further increased due to infection or sepsis." (PMID 33920604, 2021). "We report an influence of leptin levels on the association between obesity and insulin and NEFA in young children that is not observed in adolescents." (PMID 35071145, 2021). "During obesity, circulating leptin increases while adiponectin decreases." (PMID 33554957, 2021). "Early after the administration of a high-fat diet (HFD), the sustained increase of caloric intake induces hyperphagia and glucose intolerance, which are followed by a compensatory increase in leptin and insulin secretion prior to the onset of obesity and diabetes." (PMID 34015524, 2021). "Interestingly, a partial decrease of circulating leptin in obesity reestablishes hypothalamic leptin sensitivity and effectively reduces weight gain and enhances insulin sensitivity." (PMID 34248937, 2021). "Adipokines including adiponectin and leptin represent key players in obesity-related disorders and might be involved in the pathogenesis of NAFLD and HCC." (PMID 33925827, 2021).
Obesity (continued). "The mechanism behind lower NT‐proBNP with increasing HbA1c is unclear, but may be related to adipocyte overexpression of cytokines (the leptin‐neprilysin‐aldosterone axis), insulin resistance, or simply impaired neurohormonal hemostasis in obesity." (PMID 33998259, 2021). "Unlike other common models of obesity such as the leptin-deficient ob/ob or leptin-receptor deficient db/db mice, Ay/a mice express both a functional leptin gene and a leptin receptor." (PMID 34604220, 2021). "Moreover, elevated leptin in obesity contributes to increase blood pressure through increased renal sympathetic activity and oxidative stress in VSMC, reducing vasodilation." (PMID 34578869, 2021). "At this time, however, the connections between obesity, circulating leptin concentrations, and PD-1 expression remain unclear, particularly in cancer patients." (PMID 34421889, 2021). "Only one miRNA, miR-6803-3p, showed a statistically negative association with leptin, while leptin was associated with all three obesity indicators (p < 0.05 for all relations)." (PMID 34440082, 2021). "More recent results from a meta-analysis performed on 1372 obese individuals (BMI > 30 kg/m2) and 1616 controls, however, concluded that an association between obesity and LEP G2548A polymorphism did not exist." (PMID 34208585, 2021). "Additionally, obesity was mostly experimentally induced with specific genetic manipulations targeting the leptin signaling." (PMID 35097026, 2021). "The possible mechanisms may be due to obesity-related molecules, such as leptin, adiponectin, TNF-α, and IL-6, and their subsequent signal pathways." (PMID 33842335, 2021). "It hasbeen observed that obesity promotes hyperleptinemia and leptin resistance." (PMID 34879109, 2021). "Moreover, the administration of the reverse CB1R agonist restores leptin sensitivity and has an anti-obesity effect in mice." (PMID 33530406, 2021). "Moreover, obesity promotes the hypothalamic expression of the protease Bace1, which produces elevate levels of hypothalamic Aβ peptide and promotes leptin resistance in the hypothalamus." (PMID 34827650, 2021). "Even though the mechanisms underlying obesity-induced oxidative stress are not entirely clear, elevated leptin seen with obesity has been considered as a mechanism for regulating energy expenditure and mediating a pro-inflammatory state." (PMID 34829546, 2021). "Leptin insensitivity.Protection against obesity, increases insulin sensitivity." (PMID 34502119, 2021). "Thus, in this study, we explored the regulation and molecular mechanism of the leptin signaling pathway in obesity-related OA." (PMID 34457118, 2021). "Leptin has become a marker of tumorigenesis in overweight, obesity, and post-menopausal women." (PMID 33482868, 2021). "Therefore, obesity-induced elevation in breast adipose leptin and reduction in adiponectin play a significant role in establishing a breast microenvironment conducive to cellular transformation and tumor growth." (PMID 33859943, 2021). "Two major adipokines secreted by adipose tissue are leptin and adiponectin, which have widely been shown to promote or inhibit breast cancer, respectively, by directly interacting with breast cancer cells and by regulation of metabolic homeostasis in obesity." (PMID 33859943, 2021). "In addition to the regulation of hunger and satiety, leptin also has pro-inflammatory properties, further contributing to a chronic inflammatory state in individuals suffering from obesity." (PMID 33920604, 2021). "Méndez-Hernández analyzed the serum and tissue samples of primary BC patients in Mexican that received neoadjuvant therapy and confirmed that the polymorphisms of Leptin (LEP rs7799039) and adiponectin (ADIPOQ rs1501299) were risk-contributing factors in overweight/obesity patients." (PMID 34350120, 2021). "Leptin is an adipocyte-produced hormone that is upregulated in obesity." (PMID 34327017, 2021).
Obesity (continued). "Leptin secretion in individuals with obesity is chronically higher than lean subjects." (PMID 34220807, 2021). "This could result in CP dysfunction at the CP-CSF interface in obesity and T2DM with a deficiency of leptin cellular signaling." (PMID 34063911, 2021). "Some authors did not report any association between LEP rs7799039 genetic variants and obesity-related variables." (PMID 34205732, 2021). "Apparently, maternal leptin supports insulinsensitivity in the consumption of obesogenic food by theoffspring, which may also work against obesity development." (PMID 34782887, 2021). "However, the infusion of tocilizumab in combination with exercise training for 12 weeks significantly decreased the circulating leptin levels in people with obesity." (PMID 33572989, 2021). "This is consistent with the notion that leptin is a mediator in obesity-induced HT via neurogenic mechanisms and the activation of the renin-angiotensin system, and thus may indirectly promote cardiac hypertrophy, fibrosis and ventricular remodelling." (PMID 34679472, 2021). "The data presented in this work showed that leptin may be one of the initiating factors of obesity-related OA." (PMID 34457118, 2021). "In obesity, the production of leptin increases, and the secretion of adiponectin is suppressed." (PMID 34568346, 2021). "However, the administration of LGG at a high dose increased leptin responsiveness to exogenous leptin treatment in mice with obesity induced by a high-fat diet." (PMID 32846917, 2020). "It was confirmed that obese patients had a higher level of leptin compared to individuals with normal weight, which might be due to the leptin resistance in obesity." (PMID 33198735, 2020). "Conditional disruption of neuronal cilia, either throughout the central nervous system or from pro-opiomelanocortin (POMC)-expressing cells in the hypothalamus, results in hyperphagic-related obesity in mice and is accompanied by elevated levels of serum insulin, glucose, and leptin." (PMID 33139642, 2020). "Obesity is characterized by increased and decreased levels of leptin and adiponectin, respectively." (PMID 33202604, 2020). "The purpose of this brief review is to highlight recent studies that have explored whether the sexual dimorphism in obesity-induced sympathoexcitation is due to sex differences in the actions of two metabolic hormones, leptin and insulin." (PMID 32160920, 2020). "In addition, obesity is accompanied by leptin resistance (‘hyperleptinemia’) which leads to the activation of the immune cells." (PMID 33182462, 2020). "Moreover, the potential of asiatic acid as an anti-obesity agent can be proved from the facts that it suppresses weight gain, and enhance the sensitivity of leptin and insulin." (PMID 33013406, 2020). "The effects of nesfatin-1 on sympathetic nervous system activity could be a target for new anti-obesity drugs in leptin resistant people suffering from obesity." (PMID 33192583, 2020). "According to these findings, we can reasonably speculate that leptin links obesity and psoriasis potentially via modulating the expression level of diverse chemokines within the circulation." (PMID 33597945, 2020). "In contrast to leptin, adiponectin circulating levels are lower in obesity and type 2 diabetes." (PMID 33292104, 2020). "In obese but normally cycling females, the variable effect of leptin on SNA during the reproductive cycle may contribute to the poor correlation of SNA to indices of obesity." (PMID 32160920, 2020). "In the same way, leptin serum levels are related to obesity and adipocytes’ repletion." (PMID 32630168, 2020). "Leptin levels are increased in gestational diabetes with obesity." (PMID 32630697, 2020). "Mutations in genes that have a physiological role in the hypothalamic leptin–melanocortin energy balance system, such as mutations in leptin, leptin receptor, POMC, prohormone 1/3 convertases (PC1/3), MC4R, are related to the currently known monogenic forms of obesity." (PMID 33261141, 2020).
Obesity (continued). "There is a correlation between obesity and a high level of serum leptin." (PMID 33369452, 2020). "The obesity status and female sex may exert modification effect on transcription of LEP, particularly in obese women." (PMID 31914480, 2020). "Therefore, it is essential to measure leptin levels to inform healthcare management of obesity and obesity-mediated diseases." (PMID 33374256, 2020). "Thus, inhibition of PAI-1 activity is a potential therapeutic strategy for fighting obesity via alleviation of leptin resistance." (PMID 32670063, 2020). "Cytokines are closely related to obesity, such as resistin, leptin, adiponectin, and TNF-α." (PMID 32439940, 2020). "Leptin is thought to play some role in obesity and insulin resistance." (PMID 33489589, 2020). "The data collected indicated LEP mutation, absence of detectable circulating leptin, and severe obesity, providing evidence of the first monogenic leptin deficiency reported in North and South America." (PMID 33261141, 2020). "At first, scientists thought leptin would be the key to control obesity." (PMID 33322719, 2020). "Leptin plasma levels increase in proportion to overall obesity." (PMID 33019728, 2020). "Leptin resistance of vagal afferents leads to hyperphagia and an obesity phenotype." (PMID 33353562, 2020). "Additionally, leptin’s effects on obesity and insulin resistance are mediated by pro-opiomelanocortin (POMC)." (PMID 32131811, 2020). "Therefore, a number of therapeutic strategies against obesity have focused on reducing insulin/leptin resistance." (PMID 33218042, 2020). "However, in spite of high leptin levels during obesity, a failure in the essential leptin mechanisms (reduction in feeding behavior and increased energy expenditure) is present due to leptin resistance." (PMID 32982666, 2020). "Macrophage secreted-adipokines such as TNF-α and IL-6 can induce low grade inflammation; thus, obesity could lead to insulin resistance (IR), increased leptin, and decreased adiponectin." (PMID 32961822, 2020). "Leptin is the best-characterized adipokine whose circulating plasma concentration correlates with the amount of adipose tissue and therefore is increased in obesity." (PMID 32231659, 2020). "Indeed, leptin intake at physiological doses during the suckling period in rats has been reported to exert long-term protective effects against the development of obesity and related metabolic alterations in adulthood." (PMID 32825787, 2020). "Leptin might thus be required for GDF11-induced adiponectin secretion during obesity, and a significant correlation between circulating GDF11 and leptin levels has been found in obese patients." (PMID 33126224, 2020). "Whether the association of leptin, CYP1B1 and AhR ligands is correlated in adult obesity, in association with a decreased CD8+ T cell and NK cell cytotoxicity, as some data could suggest, will be important to determine." (PMID 33375613, 2020). "Leptin is a polypeptide hormone produced by adipocytes and is considered a pro-inflammatory adipokine involved in the “low-grade inflammatory state” described in overweight and with obesity patients." (PMID 33192583, 2020). "Furthermore, the HPA axis is activated in response to stressful situations, including academic stress, leading to the release of cortisol (a stress hormone) and leptin (an anti-obesity hormone)." (PMID 32785011, 2020). "To investigate mucus function during obesity not confounded by diet, we compared genetically obese (ob/ob) leptin-deficient mice with their lean, separately housed littermates that were all fed a fiber-containing control chow diet." (PMID 32900852, 2020). "Likewise, lactoferrin can alleviate obesity by inhibiting leptin production and controlling LPS releasing from gut microbiota." (PMID 33195370, 2020). "Furthermore, certain hormones (such as leptin) and the composition of a person’s intestinal flora are being discussed as relevant influencing factors for obesity." (PMID 35146282, 2020).